HTR1B (5-hydroxytryptamine receptor 1B)
Description:
G protein-coupled receptor for 5-hydroxytryptamine (serotonin). Also functions as a receptor for ergot alkaloid derivatives, various anxiolytic and antidepressant drugs and other psychoactive substances, such as lysergic acid diethylamide (LSD). Ligand binding causes a conformation change that triggers signaling via guanine nucleotide-binding proteins (G proteins) and modulates the activity of downstream effectors, such as adenylate cyclase. HTR1B is coupled to G(i)/G(o) G alpha proteins and mediates inhibitory neurotransmission by inhibiting adenylate cyclase activity. Arrestin family members inhibit signaling via G proteins and mediate activation of alternative signaling pathways. Regulates the release of 5-hydroxytryptamine, dopamine and acetylcholine in the brain, and thereby affects neural activity, nociceptive processing, pain perception, mood and behavior. Besides, plays a role in vasoconstriction of cerebral arteries.
Synonyms: 5-HT-1B; 5-HT1B; 5-HT-1D-beta; HTR1DB; S12; HTR1D2; 5-HT1DB
Tractability: Small molecule: an approved drug acts on it; a structure with a bound ligand is known; a high-quality ligand is known; it belongs to a druggable protein family. Antibody: UniProt places it where antibodies can reach, with high confidence; its Gene Ontology location is reachable by antibodies, with high confidence; UniProt predicts a signal peptide or a membrane-spanning region; the Human Protein Atlas places it where antibodies can reach. PROTAC: a small molecule that binds it is known. Other modalities: an approved drug acts on it.
Target class: Monoamine receptor; Family A G protein-coupled receptor; Small molecule receptor (family A GPCR); Serotonin receptor; Membrane receptor
Safety:
Unwanted effects reported when the protein is acted on. In parentheses: how it was acted on, where the effect was seen, and who reports it.
increased aggression (Bowes et al. (2012): inhibition, cardiovascular system, central nervous system; Lynch et al. (2017): inhibition, acute dosing, nervous system, cardiovascular)
increased blood pressure (Lynch et al. (2017): activation, acute dosing, nervous system, cardiovascular; Bowes et al. (2012): activation, cardiovascular system, central nervous system)
cerebral and coronary artery vasoconstriction (activation; cardiovascular system, central nervous system; source: Bowes et al. (2012))
decreased aggression (activation, acute dosing; nervous system, cardiovascular; source: Lynch et al. (2017))
decreased anxiety (inhibition, acute dosing and activation, acute dosing; nervous system, cardiovascular; source: Lynch et al. (2017))
decreased body temperature (activation, acute dosing; nervous system, cardiovascular; source: Lynch et al. (2017))
decreased eating (activation, acute dosing; nervous system, cardiovascular; source: Lynch et al. (2017))
decreased memory (activation, acute dosing; nervous system, cardiovascular; source: Lynch et al. (2017))
decreased pain (activation, acute dosing; nervous system, cardiovascular; source: Lynch et al. (2017))
increased memory (inhibition, acute dosing; nervous system, cardiovascular; source: Lynch et al. (2017))
adverse cognitive effects (source: ClinPGx)
becoming agitated (source: ClinPGx)
suicidal ideation (source: ClinPGx)
Gene: Protein-coding gene on chromosome 6 (77,460,924 to 77,463,491, reverse strand). Ensembl gene ENSG00000135312.
Subcellular location: Cell membrane
Subcellular location (Human Protein Atlas): Plasma membrane; Endoplasmic reticulum
Pathways (Reactome):
Signal Transduction: G alpha (i) signalling events; Serotonin receptors
Gene Ontology:
Molecular function: G protein-coupled serotonin receptor activity; Gi/o-coupled serotonin receptor activity; protein binding; neurotransmitter receptor activity; G protein-coupled receptor activity; serotonin binding
Biological process: adenylate cyclase-inhibiting G protein-coupled receptor signaling pathway; adenylate cyclase-inhibiting serotonin receptor signaling pathway; cellular response to alkaloid; cellular response to xenobiotic stimulus; positive regulation of vascular associated smooth muscle cell proliferation; chemical synaptic transmission; G protein-coupled receptor signaling pathway, coupled to cyclic nucleotide second messenger; negative regulation of serotonin secretion; bone remodeling; G protein-coupled receptor signaling pathway; phospholipase C-activating serotonin receptor signaling pathway; regulation of behavior; vasoconstriction
Cellular component: plasma membrane; dendrite; cytoplasm; G protein-coupled serotonin receptor complex; membrane; presynaptic membrane; serotonergic synapse
Genetic constraint (gnomAD): Loss-of-function variants: 12 observed, 27.06 expected, observed/expected ratio (o/e) 0.44, 90% interval 0.28 to 0.72. The upper end of that interval is the gene's LOEUF score, 0.72, which puts it in group 2 of 6, group 1 being the genes least tolerant of losing a copy. Missense variants: 453 observed, 537.23 expected, observed/expected ratio (o/e) 0.84, 90% interval 0.78 to 0.91. Synonymous variants: 224 observed, 235.66 expected, observed/expected ratio (o/e) 0.95, 90% interval 0.85 to 1.06.
Homologues: Orthologues: chimpanzee HTR1B (100% identical), macaque HTR1B (98% identical), pig HTR1B (95% identical), dog HTR1B (95% identical), rabbit HTR1B (93% identical), rat Htr1b (93% identical), mouse Htr1b (92% identical), guinea pig HTR1B (89% identical), tropical clawed frog htr1b (77% identical), Drosophila melanogaster 5-HT1A (40% identical), Drosophila melanogaster 5-HT1B (36% identical). Paralogues in human: HTR1E (45% identical), HTR1F (44% identical), HTR7 (34% identical), HTR5A (32% identical), HTR2B (27% identical), HTR2A (27% identical), HTR6 (26% identical), HTR2C (26% identical).
Diseases named in the same sentence as HTR1B in open-access papers:
HTR1B is named in the same sentence as 96 diseases in open-access papers, as found by Europe PMC text mining. Sharing a sentence is not in itself a finding about the gene and the disease. The quoted sentences say what the papers report.
migraine (47 papers, 2008 to 2025). "Htr1b and Htr1d agonists, like triptans, are effective in treating migraine." (PMID 39569210, 2024).
depression (34 papers, 2008 to 2025). "A study in African American/Caucasian versus Hispanic/Asian/other populations found a significant association of the HTR1B G861C gene locus with substance use disorders and major depressive disorder." (PMID 39731452, 2025). "Cefaclor consistently modulated mRNA expression of Htr1a, Htr1b, and Htr6 receptors, which are implicated in pathology of anxiety and depression, in the hippocampus." (PMID 37726354, 2023). "Among them, the gene encoding the 5-HT1B receptor (HTR1B) has been correlated to attempted suicide in patients with major depression, because altered postmortem 5-HT1B receptor binding was found to be associated with suicide in some of the studies." (PMID 22619623, 2012). "Genetic associations of HTR1B have been examined with various psychiatric conditions such as antisocial behaviors, suicide, depression, and schizophrenia." (PMID 21886584, 2011). "Htr1b encodes the subunit beta 1 of the 5-hydroxytryptamin receptor, important in memory processing, and whose higher transcriptional levels have been associated with depression, bipolar disorders, and schizophrenia." (PMID 39329756, 2024). "Additionally, there is an association between depression and the SNP rs6296 of HTR1B, HTR2A rs6561333 with cocaine dependence, HTR3B rs11606194 over time to relapse after smoking cessation and with nicotine dependence, and HTR3B rs1176744 with alcohol and nicotine dependence." (PMID 39731452, 2025). "This study aims to estimate the contribution of 11 polymorphisms in the genes SLC6A4 (5HTT), HTR1A, HTR2A, HTR1B, SLC6A3 (DAT1), DRD4, DRD2, COMT, and BDNF to suicidal behavior and severity of symptoms of depression and anxiety in the Russian population." (PMID 34199792, 2021). "For example, lower functioning of 5-HT1B receptors was found in patients suffering major depressive disorders, while a polymorphism at the 5-HT1B receptor gene (HTR1B) was reported to be associated significantly with alcoholism." (PMID 24688470, 2014). "Additionally, we evaluated the role of the SNP sites of HTR1A, HTR1B, S100A10, BDNF genes in depression patients through genetic association analysis." (PMID 39130405, 2024). "In this study, we estimated the contribution of SLC6A4 (5HTT), HTR1A, HTR2A, HTR1B, SLC6A3 (DAT1), DRD4, DRD2, COMT, and BDNF genes to the suicidal behavior and severity of symptoms of depression and anxiety in the East-Slavic population of Russia." (PMID 34199792, 2021).
Anxiety (31 papers, 2008 to 2025). Intense feelings of nervousness, tension, or panic often arise in response to interpersonal stresses. "Research also suggests a possible correlation between specific haplotypes of the DHEA-producing enzyme cytochrome P450 CYP17A and the C861 allele of the serotonin receptor 1Dβ gene (HTR1B) and severity of anxiety in those with AN." (PMID 38685102, 2024). "Another core gene, HTR1B, encoding a serotonin receptor, was associated with SUD, anxiety, and neuroticism." (PMID 37937232, 2023). "HTR1B is a GPCR known to affect anxiety and inhibit cognition in vertebrates, possibly via cholinergic and glutamatergic inhibition." (PMID 37626835, 2023). "HTR1B is involved in serotonin synthesis, which affects behavior and anxiety in animal models." (PMID 39130405, 2024). "As candidate genes, this study selected three serotonin (5-HT) receptor genes htr1Aa, htr1B, and htr2B, as well as the two 5-HT transporter genes slc6a4a and slc6a4b for their involvement in the regulation of the serotonergic system and in anxiety related behaviors." (PMID 32275662, 2020). "Involvement of other 5-HT receptors including HTR1B, HTR1B, and HTR2C in the mechanisms of anxiety have also been recognized." (PMID 33178009, 2020). "HTR1A, HTR1B, HTR2A, and HTR2B were commonly targeted in preclinical studies for the anxiety treatment as well as the anxiolytic-like studies of SZJ." (PMID 33178009, 2020). "Currently, though the alteration of GABAA and 5-HT receptors under strong oxidative stimulation is unclear, our result in some extent suggested that overexpression of GABRA1, GABRA2, HTR1A, HTR1B, and HTR2A may be involved in oxidative stress-induced anxiety." (PMID 33178009, 2020).
schizophrenia (12 papers, 2011 to 2025). A major psychotic disorder characterized by abnormalities in the perception or expression of reality. "Further analysis using the Kruskal–Wallis test revealed significant differences in the scores of all individual items on the BARS scale between haloperidol-treated schizophrenia patients carrying different genotypes of the HTR1B rs13212041 polymorphism." (PMID 32231051, 2020). "HTR1B polymorphisms are associated with schizophrenia in the northern Han Chinese population, which provides an etiological reference for schizophrenia." (PMID 30231895, 2018). "Although sex differences are essential to study to fully understand the etiology of schizophrenia, unfortunately, few studies have been made regarding gender-specific associations between HTR1B and schizophrenia." (PMID 30231895, 2018). "In this study, the HTR1B gene was found to be related to gender in schizophrenia, as the rs1778258 A-allele caused increased risk of schizophrenia in male patients." (PMID 30231895, 2018). "Prior studies addressing the association between schizophrenia and HTR1B polymorphisms in the Chinese Han population include only the 5′-untranslated (5’UTR) and coding regions, with little data concerning the 5′-promoter and 3′-regulatory regions." (PMID 30231895, 2018). "Therefore, we proposed that ERVWE1 impaired the plasticity of 5-HT neurons by activating the HTR1B signaling pathway to regulate synaptic plasticity-associated gene expression in schizophrenia." (PMID 37990254, 2023). "Intriguingly, we discovered a positive correlation between HTR1B and the m6A demethylase ALKBH5 in schizophrenia patients (p < 0.05, correlation coefficient = 0.52), suggesting that aberrant expression of HTR1B might be associated with m6A demethylation." (PMID 37990254, 2023). "Interestingly, a similar sex-dependent relationship between HTR2C gene variants and suicidal behavior and HTR1B polymorphisms and schizophrenia has been reported." (PMID 36551873, 2022). "Since it is known that these neurotransmitter systems are closely related, these differences may contribute to the gender-specific relationship between HTR1B polymorphisms and schizophrenia." (PMID 30231895, 2018). "However, when we compared the SAS, BARS and ESRS total scores in schizophrenia patients carrying different genotypes or alleles of the 5-HT receptor gene polymorphisms, we found a significant association of the HTR1B rs13212041 polymorphism with the total BARS scores." (PMID 32231051, 2020). "HTR1B 5′ regulatory region polymorphisms have regulatory effects on gene expression and may correlate with several pathological and physiological conditions, such as weight gain and schizophrenia." (PMID 33036580, 2020). "Therefore, linkage disequilibrium of HTR1B could be associated with schizophrenia in northern Han Chinese peoples." (PMID 30231895, 2018). "In conclusion, we proposed that HTR1B was subjected to m6A modification and associated with the ERK pathway in schizophrenia based on our bioinformatics analysis." (PMID 37990254, 2023). "As our GOBP analysis indicated abnormal mRNA modification in schizophrenia, we also examined the correlation between HTR1B and m6A modification-related genes, which are the most prevalent mRNA modification." (PMID 37990254, 2023). "Overall, HTR1B, Arc, and ALKBH5 levels were increased in schizophrenia and positively associated with ERVWE1." (PMID 37990254, 2023). "Taken together, ERVWE1 impaired neuronal plasticity in schizophrenia by activating the HTR1B signaling pathway in an m6A-dependent manner, and ALKBH5 was involved in these processes." (PMID 37990254, 2023). "ALKBH5 was a new risk gene for schizophrenia, and it is significantly related to HTR1B in schizophrenia patients." (PMID 37990254, 2023). "We observed a significant increase in both the mRNA expression level (p < 0.05) and plasma protein concentration of HTR1B (p < 0.001) in first-episode schizophrenia." (PMID 37990254, 2023).
schizophrenia (continued). "The consistent results suggested that ERVWE1 weakened 5-HT plasticity by activating the HTR1B signal pathway to regulate Arc expression in schizophrenia." (PMID 37990254, 2023). "Further studies established that ERVWE1 impaired 5-HT plasticity through the HTR1B signal pathway in an ALKBH5-m6A-dependent manner in schizophrenia." (PMID 37990254, 2023). "In this paper, we demonstrated that ALKBH5 and HTR1B were increased in first-episode schizophrenia and displayed a strong correlation with ERVWE1." (PMID 37990254, 2023). "Applying of a post-hoc Dunn’s multiple comparisons test demonstrated that haloperidol-treated schizophrenia patients carrying the HTR1B rs13212041 TT genotype had a significantly higher total BARS scores (p = 0.007) than carriers of the CT genotype." (PMID 32231051, 2020). "The 5-hydroxytryptamine receptor 1B gene (HTR1B) is associated with multiple psychiatric disorders, including schizophrenia, aggressive behavior, attention deficit hyperactivity disorder (ADHD), and substance abuse." (PMID 32689951, 2020). "The present paper describes the results of an association study of in the end 24 polymorphic variants of HTR1A, HTR1B, HTR2A, HTR2C, HTR3A, HTR3B, and HTR6 genes with TD and two of its subtypes in 449 patients with schizophrenia." (PMID 32390801, 2020). "This study aimed to examine molecular associations of HTR1A, HTR1B, HTR2A, HTR2C and HTR6 gene polymorphisms with acute EPS in 229 male schizophrenia patients, following two weeks of haloperidol monotherapy." (PMID 32231051, 2020). "The AAAC haplotype comprising rs6297, rs130058, rs1213366, and rs1213371 is significantly more frequent in female Spanish patients, which corroborates our finding that HTR1B genotype is related to gender in schizophrenia." (PMID 30231895, 2018). "This study presents information on the linkage state of HTR1B in schizophrenic patients of northern Han Chinese descent, and thereby provided references for the etiology of schizophrenia in different populations." (PMID 30231895, 2018). "Expanding sequences were investigated in our study, including a 2285 bp 5′-promoter region and a 1277 bp 3′-untranslated region, in the northern Han Chinese population to further explore the relationship between HTR1B and schizophrenia." (PMID 30231895, 2018). "Combining all results of this study, we assert that HTR1B has a putative relationship with schizophrenia in the northern Han Chinese population, which provides a reference schizophrenia etiology." (PMID 30231895, 2018). "To further investigate the relationship between ERVWE1 and HTR1B in schizophrenia, we transfected ERVWE1 into the human neuroblastoma cell line SH-SY5Y, which is commonly used to study neuropsychiatric disorders, to gain a deeper understanding of their association." (PMID 37990254, 2023). "In addition to HTR1B, other 5-HT receptors, including HTR1A, HTR2A, HTR3, HTR4, and HTR6 are associated with schizophrenia." (PMID 37990254, 2023). "Importantly, the analysis of DEGs revealed an elevated level of HTR1B in the prefrontal cortex (PFC) (BA46) of individuals with schizophrenia compared to healthy controls (p = 0.034), while the expression of HTR2A was significantly decreased (p = 0.005)." (PMID 37990254, 2023). "In our study, we reported a higher level of HTR1B in the blood of first-episode schizophrenia patients compared to healthy controls, suggesting that HTR1B may serve as a potential new blood biomarker for schizophrenia." (PMID 37990254, 2023). "Higher transcript levels of HTR1B have been reported in schizophrenia." (PMID 37990254, 2023). "Similarly, when akathisia was evaluated using the ESRS scale, we observed significant differences in the scores between haloperidol-treated schizophrenia patients carrying different HTR1B rs13212041 genotypes (p = 0.011; Kruskal–Wallis test)." (PMID 32231051, 2020).